VHL (von Hippel-Lindau tumor suppressor)
Diseases named in the same sentence as VHL in open-access papers (continued):
Sharing a sentence is not in itself a finding about the gene and the disease.
tumor (continued). "Second, transcriptomic and proteomic profiling of 786-O-Ctrl and 786-O-VHL cells confirms the predominant role of VHL in antagonizing HIF signaling and the tumor-promoting pathways that are centrally regulated by HIF." (PMID 35159281, 2022). "A study comparing lncRNA expression profile in VHL-wild type and VHL-mutant RCC cell lines and demonstrated that LncRNA-SARCC is differentially regulated in a VHL dependent manner in RCC cell lines and tumor samples." (PMID 33922974, 2021). "When the cancer progress, oxygen within the necrotic tumor-core becomes depleted, resulting in hypoxia and a higher intracellular level of hypoxia inducible factor (HIF-1α and HIF2α) through degradation of VHL." (PMID 34131104, 2021). "Inactivated VHL results in an increased amount of hypoxia-inducible factor (HIF), which plays a role in the transcription of key genes related to tumor survival, including vascular endothelial growth factor (VEGF)." (PMID 33350295, 2021). "MiR-21 promotes cell proliferation and invasion via the VHL/PI3K/AKT pathway, and probably its expression increases as tumor grows or spreads." (PMID 33801319, 2021). "Tumour suppressors that repress this pathway, namely PTEN,VHL, LKB1 and prolyl hydroxylases are epigenetically silenced via promoterhypermethylation, contributing to deregulation of cellular energetics." (PMID 33465324, 2021). "The VHL-HIFα–EGFR pathway increases the proliferation and survival of RCC tumor cells through downregulation of RAF–MEK–ERK." (PMID 34575959, 2021). "On the basis of our study, VHL, SIRT4, HIF-1α, and HO-1 were genes related to a few tumor-related biological processes, including metabolism, cancer development, and cellular stress response." (PMID 34135317, 2021). "Recent study showed that HIF1α was essential for tumor formation and HIF-1α regulates glycolysis 31, our data further supported the notion that KDM5C partially inhibited the elevated expression of HIF1α- and metabolism-related genes, which may be caused by loss of VHL." (PMID 34522206, 2021). "VHL gene protein can inhibit the hypoxia inducing factor (HIF) and function in inhibiting the tumor." (PMID 33665156, 2020). "VHL(-) cells also facilitate, in a HIF-independent manner, intracellular nutrients by activation of LC3B-mediated autophagy, which are necessary for tumor growth." (PMID 33643028, 2020). "One of the most interesting examples is miR-210, which is known to be regulated by the VHL/HIF-pathway and has emerged as a novel indicator for ccRCC tumor burden." (PMID 33194717, 2020). "In arsenite-mediated tumor development in hepatic epithelial cells, MALAT1 promotes HIF-2α stabilization by enhancing its dissociation from VHL." (PMID 32640630, 2020). "Additionally, because there are limited GWAS data available on patients who also have tumor molecular data, we did not validate the observed associations between the 8q24 germline variant and VHL tumor mutation nor the association between the EPAS1 germline variant and SETD2 tumor mutation." (PMID 33121461, 2020). "In the following studies, the VHL genotype should be taken into consideration to determine whether surgical treatments are needed or not, to predict the risk of tumor recurrence, progression, and metastasis, and to predict therapeutic effects of non-surgical interventions." (PMID 33362845, 2020). "pVHL, the protein product of the VHL tumor suppressor gene, is a component of an E3 ubiquitin ligase complex." (PMID 30585695, 2019). "Therefore, and due to the lack of effective therapies for diffuse or recurrent disease, there is an urgent demand for effective drugs for VHL patients, especially those medicines that might halt the progression of tumours and subsequently delay surgical treatment." (PMID 31296894, 2019).
tumor (continued). "The expression of VHL related negatively to tumour LBD (univariate regression analysis, p = 0.034), with larger tumours having lower VHL." (PMID 31323773, 2019). "These included mutations in the well-known ccRCC-specific cancer driver genes VHL and PBRM1, which were, therefore, most likely involved in the initiation of tumour development in this patient." (PMID 31212796, 2019). "Previously we have described that RWDD3 or RSUME (RWD domain-containing protein SUMO Enhancer) sumoylates and binds VHL protein and negatively regulates HIF degradation, leading to xenograft RCC tumor growth in mice." (PMID 30890701, 2019). "Von Hippel Lindau (VHL) expression is significantly decreased in high-grade RCC, and autophagy, which is involved in tumor growth, invasion, differentiation, and metastasis, is activated in various human cancers." (PMID 30902965, 2019). "Although biallelic VHL inactivation and the resulting activation of HIF and its targets seem to be necessary for tumor development, other activating factors are also needed for initiation of tumor progression." (PMID 31087189, 2019). "Neither presence of RCC, EPO-level, associated tumor cysts nor VHL-mutation (truncating versus non-truncating) had any significant impact in predicting polyglobulia By performing multivariate binary regression again only tumor volume was a robust independent predictor for polyglobulia." (PMID 30214643, 2018). "Our results show a 100% specificity of the cytopathological diagnosis of CCC, based on concordance of VHL genetic profiles obtained from all the CCC and corresponding tumor samples." (PMID 29732003, 2018). "This seems to be especially evident in VHL-defective ccRCC, where HIF-1 can have tumor suppressive effects, whereas HIF-2 appears to be the major player in tumorigenesis and is associated with higher grade, stage and poor patient outcome." (PMID 30555801, 2018). "Constitutive HIF activation was shown as required for serum-independent growth of 786-0 VHL−/− RCC cells in culture, as well as for tumour formation in xenograft nude mice by these cells." (PMID 29455394, 2018). "5-Aza-2′-deoxycytidine also re-expressed VHL both in RCC cell lines and in xenograft murine tumors, significantly reducing tumor size of ccRCC xenograft in mice." (PMID 29706891, 2018). "We also found an identical VHL gene sequence to that of the corresponding tumor samples in 85.1% of CRC-UMF from the 29 cases, including four patients harbouring wild type VHL sequences in all their CRC-UMF and corresponding tumors." (PMID 29732003, 2018). "However, two of these 11 patients harboured double missense VHL mutations in the tumor tissue that were found identical in the corresponding CRC (including seven CCC and seven CRC-UMF) and could presumably be located on the two VHL alleles, leading to pVHL LOF." (PMID 29732003, 2018). "Partial response or stable disease were observed in the patient with a VHL mutation and five of the six evaluable patients with an SDHB mutation, suggesting that patients with cluster 1 disease might be better responders to antiangiogenic treatments than patients with cluster 2 tumours." (PMID 28471419, 2017). "Ablation of the HIF-1 negative regulator, VHL, boosts cytolytic CD8+ T cell responses, enhancing viral clearance and suppressing tumor growth." (PMID 28542595, 2017). "The most common 44 genes (p<0.001) including VHL enlist MON1A, CCDC51 and TMA7 at 3p21.31 (31/29 HRO tumours), and MIRLET7G and WDR28 at 3p21.1 (31/31 tumours), respectively." (PMID 28486536, 2017). "Allelic losses or hypermethylations on the 3p region has been observed more frequently in tumors with a squamous histology compared with adenocarcinoma, involving some tumor suppressor genes such as RASSF1A, FUS1, VHL, and FHIT." (PMID 28591695, 2017).
tumor (continued). "Besides, some recent researches about the mechanism of tumor-suppressor proteins, such as PML and VHL, revealed that the pathogenesis of tumors included not only the lack of some tumor-suppressor proteins and their mutation, but also their abnormal nuclear localization and rapid degradation." (PMID 28187431, 2017). "However, the mechanism of tumor initiation in VHL patients remains unclear." (PMID 28776935, 2017). "The discovery of VHL inactivation and HIF activation of genes and other pathways that are important for tumor progression has aided the development of new drugs that target angiogenesis and proliferation pathways." (PMID 27583351, 2017). "Meanwhile, Notch is also believed to regulate tumor cell biology via HIF function, which is a downstream of VHL gene." (PMID 27612417, 2016). "Likewise, a higher expression of mitochondrial respiration-associated genes in the tumor tissue likely also reflects the presence of stromal cells within the tumor tissue that do not have VHL mutations and thus maintain normal levels of mitochondrial metabolism." (PMID 27422173, 2016). "The published evidence now strongly suggests that in hypoxia, WSB1, through diverse mechanisms such as protection of HIF-1 through downregulation of VHL, HIPK2 and/or RhoGDI2, contributes to tumor metastasis." (PMID 27542736, 2016). "Besides VHL, other genetic alterations in subgroup-5 involve the mutation of the chromatin remodeling gene PBRM1, the mutation of the histone methyltransferase gene SETD2, which has been identified as a tumor suppressor in KIRC and high methylation rate of GSTP1." (PMID 26148869, 2015). "A recent study on the von Hippel-Lindau tumor suppressor (VHL, also known as E3 ubiquitin protein ligase) suggested that VHL inactivation decreases H3K4Me3 levels through JARID1C, which suppresses tumor growth as well as COL6A1 expression." (PMID 26317545, 2015). "The 786-O cell line is established from a ccRCC tumor that lacks functional VHL, and WT7 is a subclone of this cell line where VHL has been reintroduced." (PMID 25569102, 2015). "Somatic mutations in inherited PCC/PGL genes can be detected in ~25–30% of the sporadic tumours (mainly involving RET, VHL, NF1, MAX, and HIF2A genes)." (PMID 25883647, 2015). "Both TSC and VHL intersect with the primary cilium and the mTOR signaling network known to be upregulated in PKD and several tumor types." (PMID 24584572, 2015). "One may be a mutation or silencing of the von Hippel-Lindau (VHL) gene which is present in over 50 % of cases and is thought to lead in the accumulation of hypoxic-inducible factor 1-alpha (HIF1A), which then creates angiogenesis leading to further tumor growth and potential disease spread." (PMID 26510665, 2015). "Analysis of SNP array data showed loss of heterozygosity (LOH) located to the genomic coordinates of the respective gene in 1/1 SDHB, 11/11 VHL and 3/3 NF1-related tumours." (PMID 24466223, 2014). "Taken together, we demonstrate here that downregulation of RKIP occurs frequently at a rate that reaches that of VHL, suggesting RKIP being a critical tumor suppressor for ccRCC." (PMID 25277181, 2014). "Several signaling pathways are involved in tumor angiogenesis, such as VEGF, which plays a crucial role in RCC carcinogenesis, PDGF, the mammalian target of rapamycin (mTOR), VHL, a tumor suppressor gene, and HIF." (PMID 24093097, 2013). "To examine its contribution to tumor growth, we identified several shRNA constructs that suppressed IGFBP3 protein expression in VHL-/- cells." (PMID 24260413, 2013). "We determined that VHL, by inducing microRNA-204, inhibited LC3B-mediated autophagy which is necessary for ccRCC tumor growth." (PMID 23922894, 2013). "While the hypoxic microenvironment plays a critical role in the development and progression of tumours in general, it is of special significance in the case of RCC because of the link between VHL, HIF and EPO." (PMID 23305401, 2013).
tumor (continued). "5-AZA-CdR reactivates the tumor suppressor gene VHL in human renal carcinoma cell lines and the expression of the p16/CDKN2 tumor suppressor gene, which prevents the entry of tumor cells into the S-phase of the cell cycle, in different tumor cell lines." (PMID 23369223, 2013). "To determine if there was a functional link between FLCN and the tumor-suppressing activity of VHL, we knocked down expression of FLCN in 786-O VHL(+) cells by using three different shRNAs." (PMID 23922894, 2013). "Here we reported that VHL regulates expression of FLCN and that, in turn, FLCN participates in the tumor suppressing activity of VHL." (PMID 23922894, 2013). "Recently we have described that VHL suppresses LC3B-mediated, pro-oncogenic autophagy while it stimulates a novel tumor suppressing autophagic program, mediated by LC3C." (PMID 23922894, 2013). "Knockdown of FLCN results in increased formation of tumors by RCC cells with wild-type VHL in orthotopic xenografts in nude mice, an indication that FLCN plays a role in the tumor-suppressing activity of VHL." (PMID 23922894, 2013). "We report here that KAI1 acts in the process of tumor malignancy and angiogenesis by profoundly suppressing metastasis via inhibition of CDCP1-enhanced Src activation and functional activation of VHL." (PMID 22390300, 2012). "A number of studies have argued that in cancer, particularly in the context of VHL deletion, HIF-2α can act as the driver for malignant cell progression and tumor angiogenesis." (PMID 22264788, 2012). "We employed this model for a proteomics based approach to identify changes characteristic for tumor aggressiveness, which we then explored in a homogeneous set of human SDHB- and VHL-PHEOs/PGLs." (PMID 22859959, 2012). "Additional experiments on LDH enzyme activity or measurement of tumor lactate levels in fresh tumor tissue from SDHB- and VHL-PHEOs/PGLs will be of great interest for judging the functional impact of elevated LDHA levels in SDHB-PHEOs/PGLs." (PMID 22859959, 2012). "We followed tumor growth in vivo and immunohistochemistry was performed for detection of HIF-1, CDCP1, and VHL protein level." (PMID 22390300, 2012). "When comparing VHL- and SDHB-derived tumor tissues, in the latter we observed the expected decrease in complex II activity, but also an increase in complex III activity." (PMID 22859959, 2012). "VHL ubiquitinates and degrades the α subunits of HIF, and this is proposed to suppress tumorigenesis and tumor angiogenesis." (PMID 21386990, 2011). "JARID1C was shown to be a HIF target gene in RCC cells, but it suppresses tumor growth, suggesting that inactivation of both VHL and JARID1C is required for tumor formation in this subtype of ccRCC." (PMID 21544224, 2011). "In VHL-defective ccRCC cells, the prolonged signaling of the activated EGFR likely contributes to tumor growth." (PMID 21949687, 2011). "However how VHL exerts its tumour suppressor function remains unclear." (PMID 21791076, 2011). "The von Hippel–Lindau gene (VHL) alteration, a common event in sporadic clear-cell renal-cell carcinoma (CCRCC), leads to highly vascularised tumours." (PMID 19755989, 2009). "Median progression-free survival and CCRCC-specific survival were significantly reduced in patients with wild-type VHL or altered VHL and high VEGF expression, which, therefore, represent two markers of tumour aggressiveness in CCRCC." (PMID 19755989, 2009). "When focusing on the population with at least one VHL alteration, it appeared that both VEGF tumour expression (cut-off 30%) and VEGF plasma level (cut-off, median value of 92.5 pg ml−1) were able to stratify two population subsets with distinct outcomes." (PMID 19755989, 2009). "A biallelic VHL inactivation leads to HIF-1α accumulation and subsequent overexpression of genes, which are critical for tumour angiogenesis, cell proliferation and migration." (PMID 19755989, 2009).
tumor (continued). "The aims of this study were to analyse the relationship between VHL genetic and epigenetic alterations, VHL expression and VEGF tumour or plasma expression, and to analyse their respective prognostic value in patients with CCRCC." (PMID 19755989, 2009). "Also, the differences observed in fibronectin deposition between 786-O cell lines expressing either of the two isoforms of VHL in the present studies might indicate a more subtle role of fibronectin, since these cell lines have been shown to have equal tumor suppression ability." (PMID 17598890, 2007). "Several genes including tumour suppressor genes and DNA repair genes such as hMLH1, RB1, VHL, p15, p16, RASSF1A, MGMT and BRCA1 in human cancers were shown to be epigenetically inactivated by DNA methylation in tumours." (PMID 14970867, 2004). "Finally, we validated the anti-tumor effects of Curcumol in an orthotopic CRC model and investigated the role of VHL." (PMID 41008845, 2025). "We first validated that TYR could catalyze the in situ generation of VHL-recruiting PROTACs to efficiently degrade TYR both in vitro and in vivo for curtailing melanin synthesis to effectively treat skin hyperpigmentation." (PMID 40651969, 2025). "In KIRC, characterized by frequent VHL inactivation and constitutive HIF signaling, USP37 may preferentially target and stabilize substrates that exert tumor-suppressive or immunomodulatory functions." (PMID 40926837, 2025). "Furthermore, the VHL-HIF axis regulates GAL3ST1 in ccRCC, which affects the tumor's immune evasion capabilities." (PMID 39781455, 2025). "While YY1 promotes tumor growth by stabilizing HIF-1α levels in some types of tumors, aberrant expression of YY1 results in ccRCC by increasing the expression of HIF-2α and inhibiting VHL." (PMID 40688406, 2025). "Moreover, the inhibitory effect on the VHL/HIF-1α/VEGF signaling pathway was confirmed, supporting its role in reducing tumour growth." (PMID 41030787, 2025). "Our findings also highlight a context-dependent role for pRb in ccRCC whereby pRb functions as an oncogene in the absence of VHL, and as a tumor suppressor in the presence of VHL." (PMID 40240354, 2025). "This improvement was attributed to increased expression of both BCL-XL and VHL in tumor cells but not in platelets." (PMID 40794443, 2025). "In the context of renal cancer, for example, exosomes from tumor cells lacking the Von Hippel–Lindau (VHL) gene, a well‐known tumor suppressor, can transform normal cells, significantly increasing invasion and migration." (PMID 40318053, 2025). "A literature review on the relationship between tumor size and the metastatic potential of VHL-related RCC found no metastasis in tumors less than 3 cm." (PMID 41458689, 2025). "Firstly, under moderate hypoxia, prolyl hydroxylase activity is partially maintained, allowing a proportion of HIF-1α molecules to undergo hydroxylation and subsequent recognition by VHL, as evidenced by detectable hydroxylated HIF-1α in hypoxic tumor regions and moderately hypoxic cells." (PMID 41446875, 2025). "When VHL-induced degradation is impaired, HIF1A and HIF2A accumulate, resulting in elevated levels of erythropoietin (EPO), vascular endothelial growth factor (VEGF), and other growth factors, which promote tumor growth." (PMID 40005423, 2025). "We showed that Beclin1 P54A knock-in expression in VHL-proficient SN12C cells increased tumor volumes, weight (Fig. EV5D), and expression of Ki67 (Fig. EV5E) and LC3B expression with a corresponding decrease in p62 expression in tumor tissue." (PMID 38360997, 2024).